IL6 (interleukin 6)
Diseases named in the same sentence as IL6 in open-access papers (continued):
Sharing a sentence is not in itself a finding about the gene and the disease.
Obesity (continued). "Adipocytes contribute to the secretion of proinflammatory cytokines such as TNF-α, IL-1β, MMP-2, MMP-9, IL-6, and MCP-1, as well as adipokines like adiponectin, which further contribute to chronic inflammation in adipose tissue of individuals with obesity." (PMID 38495901, 2024). "For instance, SM (60 mg/kg) was illustrated to reduce inflammation (TNF-α, IL-1β and IL-6) and to mitigate liver damage and insulin resistance in a model of HFD-induced obesity mice." (PMID 38247522, 2024). "This is achieved through the upregulation of cytokine production (such as IL-6, TNF-a, etc.)and the recruitment of inflammatory macrophages in obesity mouse model." (PMID 38774876, 2024). "Pregnant women with obesity and PE exhibit higher leptin levels, correlating with increased Tumor Necrosis Factor-Alfa (TNF-α), Interleukin 6 (IL-6), and C-reactive protein concentrations." (PMID 38750456, 2024). "Among chronic disorders, obesity is reported to be a noteworthy promoter of inflammatory status, characterized by an increase in tumor necrosis factor-α (TNF-α), interleukin 6 (IL6), and interleukin 10 (IL10) production." (PMID 38721147, 2024). "IL6 gene expression levels were reduced in HFD-Mthistle compared to HFD-control, specifically in the eWAT, which correlates with visceral WAT in human obesity." (PMID 39683558, 2024). "In contrast, in WAT dysfunction in obesity, pro-atherogenic factors, such as FFAs, TNF-α, IL-6, resistin, and leptin, are secreted, which increase the development of atherosclerosis, internal plaque inflammation, and plaque vulnerability." (PMID 38051471, 2024). "Adipose tissue macrophages in obesity and type 2 diabetes increase TNF-α and IL-6 production in the events of a high amount of lipolysis." (PMID 38728367, 2024). "Consequently, the significant reductions in PBMC gene expressions of IL-6, IL-1β, and leptin, marked by their comparatively large effect sizes, collectively point toward a potential state of controlled inflammation in the realm of obesity subsequent to NS oil supplementation." (PMID 38178093, 2024). "Polysaccharide from Agrocybe cylindracea (ACP) has been found to ameliorate obesity in high-fat diet-induced obese mice by significantly reducing the levels of obesity-related TNF-α and IL-6." (PMID 39130633, 2024). "In mice, adipocyte-derived KYN promotes obesity and insulin resistance by activating the arylhydrocarbon receptor (AhR)/STAT3/IL-6 signaling pathway." (PMID 39125332, 2024). "It strongly inhibits the release of pro-inflammatory cytokines such as IL-6 and TNF-α, and helps ameliorate β-cell function, inflammation, and obesity." (PMID 39519546, 2024). "Obesity is a clinical manifestation of systemic OS, characterized by elevated levels of proinflammatory cytokines such as TNF-α and IL-6, which contribute to chronic low-grade inflammation." (PMID 38892561, 2024). "Increased inflammation levels in obesity are indicated by elevated levels of serum cytokines including TNF-α and IL-6." (PMID 39728103, 2024). "The cytokines IL-6, TNF-α, and leptin play critical roles in the development of obesity, insulin resistance, and chronic inflammation, which culminate into obesity-related metS." (PMID 36982743, 2023). "Among those, IL-6 and CRP are up-regulated in parallel with adipose tissue enlargement in subjects with obesity." (PMID 36902180, 2023). "The strength of our study is expressed when examining the relationship between selected measures of obesity (BMI, WC, RFM, VAI, WHtR) and parameters of chronic inflammation (CRP, TNF-α, IL-6) in perimenopausal healthy women." (PMID 37375693, 2023). "Obesity always comes with higher levels of inflammatory factors, such as tumor necrosis factor-α (TNF-α) and interleukin-6 (IL-6)." (PMID 36777345, 2023). "To determine how the expressions of the circRNAs were changed by obesity in the brain, we chose seven obesity-related blood serum factors, glucose, insulin, TNF-α, IL-6, PA, LA, and Chol, that mimic obesity in the brain." (PMID 37047207, 2023).
Obesity (continued). "Obesity is characterized by chronic low-grade inflammation, mainly mediated by adipose tissue-derived cytokines such as TNF-α and IL-6." (PMID 37834153, 2023). "In individuals with obesity, the production of pro-inflammatory adipokines (leptin, TNF-α, resistin, visfatin, IL-6, and IL-1β) is increased and that of anti-inflammatory cytokines (e.g., adiponectin) is decreased." (PMID 37364142, 2023). "This supports earlier findings showing that in individuals with obesity, adipose tissue dysfunction is a key factor contributing to low-grade inflammation, as indicated by elevated concentrations of CRP and IL-6." (PMID 36462595, 2023). "In addition, although it did not remain significant after correction for multiple testing, we found a correlation between this SNP and IL6 levels after stimulation of macrophages with LPS (p = 4.35 × 10−4), which might explain, at least in part, the link between obesity and inflammation." (PMID 37047000, 2023). "IL-6 has emerged as a key mediator of PDAC cells migration and obesity-dependent cancer development." (PMID 36074246, 2023). "IL-6 is markedly increased in patients with severe NAFLD compared with healthy patients and contributes to the development of obesity-related tumors." (PMID 37492183, 2023). "Obesity and particularly elevated levels of ROS, TNF-α, IL-6, and visfatin down-regulate the secretion of adiponectin." (PMID 37372025, 2023). "High levels of cytokines such as interleukin-6 (IL-6), interleukin-1 (IL-1) and tumour necrosis factor-alpha (TNF-α) are found amongst subjects with insulin resistance and obesity." (PMID 37624550, 2023). "The concentrations of IL-6 and IR and parameters of carbohydrate metabolism, such as HOMA, were dependent on the level of adipose tissue and increased with the degree of obesity in examined patients." (PMID 36615169, 2023). "Like TNF-α, IL-6 is related to the progression from steatosis to HCC, and its increased levels in obesity is related to several ways." (PMID 37266440, 2023). "DNA methylation regulates inflammatory cytokines, including IL-6, IL-11, and TNF-α, thus impacting the development of liver injury, diabetes, and obesity." (PMID 37020540, 2023). "Treatment with 17β-estradiol, leptin, IL-6, and TNF-α (ELIT) for obesity-related inflammation also decrease mitochondrial function and increase oxidative stress, aggressiveness, and motility in cell lines with low estrogen receptor beta (ERβ) expression." (PMID 36880535, 2023). "TLR-4 activation further stimulates the IKB kinase/nuclear factor kB (NF-kB) pathway, causing the production of proinflammatory cytokines, such as IL-6, IL-8, TNF, and IL1 (Hypothalamic Inflammation and Obesity: A Mechanistic Review)." (PMID 37764744, 2023). "Very recently it has also been shown that humans with obesity have a higher expression of vascular/perivascular TNF-α, in addition to NF-Κb and IL-6." (PMID 37109222, 2023). "Increasing serum levels of pro-inflammatory cytokines (IL-1, IL-6, and TNF-a) and acute phase proteins in obesity, especially abdominal obesity, are important mediators in bone resorption and osteoclast differentiation." (PMID 37705033, 2023). "A state of chronic inflammation, typical of conditions like obesity, T2DM, and MetS, is distinguished by the augmented expression of inflammatory adipokines, such as IL-6 and TNF-α." (PMID 37958602, 2023). "Due to adipose tissue dysfunction in states of obesity, WAT predominantly expresses proinflammatory adipokines and cytokines, such as Il-1b, Il-6, Il-12, TNF-α or interferon gamma, which contribute to the conditions of chronic systemic inflammation in obesity." (PMID 37239098, 2023). "Instead, decreases in BMI, TNF-α, IL-6, and CRP, most of them significant, were reported in the reports by Moore on the population with overweight or obesity." (PMID 37885010, 2023).
Obesity (continued). "On the other hand, studies have shown that ADSC from patients with obesity exhibits increased expression of p16INK4A and SASP components IL-6 and MCP-1 that potentially promote senescent cell accumulation in vitro." (PMID 37821967, 2023). "Obesity is characterized by a persistent, low-grade inflammation that is fueled by adipocyte-released proinflammatory mediators such TNF-α, IL-1, and IL-6." (PMID 37734921, 2023). "During obesity, the inflamed VAT is a source of pro-inflammatory adipokines including tumour necrosis factor (TNF)-α, IL-6, IL-8, CRP, or leptin, among others, that are released into the circulation promoting systemic inflammation." (PMID 36831381, 2023). "After binding with its ligand intercellular adhesion molecule 2 (ICAM-2), P9 promotes thermogenesis and improves obesity and glucose homeostasis by activating the GLP-1R signaling pathway and interleukin-6 (IL-6)." (PMID 37040299, 2023). "Furthermore, anti-obesity and insulin sensitizing effects have also been endorsed by the modulating potential of C. odorata and coumarin on adipokinin levels (leptin, adiponectin, and chemerin), and inflammatory (TNFα, IL-6) and oxidative stress biomarkers (CAT, SOD, MDA)." (PMID 37033655, 2023). "In short, whether it is potentiated by obesity and/or T2DM, inflammation is caused by changes in innate and adaptive immunity, high levels of circulating pro-inflammatory cytokines, including TNF-α, MCP-1, and IL-6, elevation of prothrombotic factors, high viral entry, and decreased viral clearance." (PMID 37888519, 2023). "Among these, 3 genes - AKT1, IL-6, and TNF - were shared between the obesity and gastric cancer sets." (PMID 37954072, 2023). "After three months of NSPT, serum (MD = -0.54, CI = -0.62 – -0.46), and GCF (MD = -2.70, CI = -4.77 – -0.63) levels of IL-6, along with the serum RBP4 (MD = -0.39, CI = -0.68–0.10) decreased in periodontitis individuals with obesity." (PMID 37798684, 2023). "Animal models with diet-induced obesity have high levels of pro-inflammatory cytokines such as TNF-α, IL-1β, and IL-6 and activation of microglia and astrocytes in the hypothalamus." (PMID 37373230, 2023). "Insulin resistance in obesity elevates oxidative stress and inflammatory cytokines, such as TNF-α and IL-6 in endothelial cells, which decreases nitric oxide bioavailability and induces endothelial dysfunction." (PMID 37790032, 2023). "Other pro-inflammatory cytokines secreted by the WAT, such as IL-6, MCP-1, and PAI-1, have been suggested to contribute to the development of insulin resistance in obesity." (PMID 37571394, 2023). "For example, obesity due to increased inflammatory cytokine levels of transforming growth factor-alpha (TGF-α) and interleukin-6 (IL-6), in addition to stress due to the fight-and-flight response, leads to the activation of cortisol and catecholamines." (PMID 36648973, 2023). "There are also some promising targeted therapies probably providing an effective medical intervention strategy for the control of obesity-related asthma, such as microRNAs, TLR antagonists, and biologics of IL-1 and IL-6." (PMID 38292857, 2023). "The aim of this study was to evaluate the effect of serum selenium on PPAR-γ and the selected proinflammatory cytokines (IL-1β, IL-6, TNF-α) in relation to depressive symptoms and obesity in middle-aged women." (PMID 37049434, 2023). "During obesity, hypertrophic adipocytes release proinflammatory adipokines and cytokines, such as leptin, visfatin, resistin, MCP-1 and IL-6, which contribute not only to local but also systemic and liver inflammation." (PMID 37189422, 2023). "We have also analyzed the relationships between plasma concentrations of sP2X7R and the most common plasmatic inflammatory markers associated with the chronic low-grade inflammation present in obesity, such as CRP, TNFα and IL-6." (PMID 38069064, 2023).
Obesity (continued). "To conclude, the adipokines adiponectin, leptin, resistin, IL-6, MCP-1 and PAI-1 produced by the adipose tissue are deregulated in the context of obesity." (PMID 38136564, 2023). "In obesity, adipose tissues produce proinflammatory cytokines such as interleukin‐6 (IL‐6) and tumor necrosis factor‐α (TNF‐α), and thus obesity is regarded as a chronic systemic inflammatory disease." (PMID 37773696, 2023). "It has been suggested that individuals with an elevated BMI, particularly those with obesity, have elevated concentrations of serum inflammatory markers, such as C-reactive protein, tumour necrosis factor alpha (TNF-α), and interleukin 6 (IL-6)." (PMID 38097936, 2023). "Obesity is related to an increased production of cytokines for the pro-inflammatory response (e.g., leptin, TNF-α, and IL-6) and a decreased secretion of adipokines that protect inflammatory response (e.g., adiponectin and IL-10)." (PMID 37821991, 2023). "For IL-1β and IL-6, two-way ANOVA revealed significant effects of obesity (F = 7.462; p = 0.0258 for IL-1β; F = 6.943; p = 0.0299 for IL-6)." (PMID 37892420, 2023). "CD4+ T cells contribute to the inflammatory state in both, HF and obesity, and promote the generation of effector CD8+ T cells, for example, via enhanced antigen presenting cell-mediated IL-6 and TNF-α production." (PMID 37885885, 2023). "This correlation is characterized by an elevation in mRNA levels of IL-6, IL-12, IFN, and CXCL10 chemokines in individuals with obesity." (PMID 38024342, 2023). "The expression of adiponectin by adipocytes is decreased in individuals with obesity, while it is also inhibited by pro-inflammatory cytokines, such as TNF and IL-6, as well as conditions such as hypoxia and oxidative stress." (PMID 37755259, 2023). "Obesity, diabetes mellitus, and metabolic syndrome are diseases mediated by proinflammatory cytokines such as TNF-α, IL-1β, and IL-6." (PMID 37685515, 2023). "Our results agree with previous findings, where obesity-induced chronic low-grade inflammation generates an increase in MCP-1, IL-1β, and IL-6 as observed in the HD group at 6 and 13 months." (PMID 37139092, 2023). "Finally, with regard to adipokines and inflammation parameters, interleukin-6 (IL-6) and leptin levels were significantly higher in patients with obesity than in normal-weight subjects, whereas adiponectin levels were significantly lower in individuals with obesity." (PMID 36833305, 2023). "Smooth muscle myocytes secrete many cytokines and other molecules, such as IL-6, TNF-α, and myonectin, related to the inflammatory process and can become inflamed in obesity, leading to increased muscle inflammation." (PMID 37492183, 2023). "Other studies showed that circulating levels of amyloid A protein, interferon-gamma (IFN-γ), interleukin-6 (IL-6), tumor necrosis factor alpha (TNF-α), and C-reactive protein (CRP) were prominently reduced in patients with obesity by CR." (PMID 37755259, 2023). "Adipocytes and macrophages in adipose tissue can produce various proinflammatory cytokines, and elevated concentrations of IL-6 and TNF-α are increased in adipose tissue and serum during obesity." (PMID 36982669, 2023). "Obesity in SLE increases the expression of interleukin 23 (IL-23), tumor necrosis factor alpha (TNF-α), IL-6, and C-reactive protein (CRP)." (PMID 36839394, 2023). "Obesity increases serum TNF-α, which induces the release of IL-6 from immune cells and adipocytes and reduces systemic anti-inflammatory cytokines, promoting systemic inflammation." (PMID 37175603, 2023). "Inflammatory biomarkers including hs‐CRP, IL‐6, IL‐4, IL‐1B, IL‐10, and TNF‐α have also been shown to be connected with obesity, diabetes, and CVD." (PMID 36911829, 2023). "For example, during the early stages of HFD-induced obesity, MMe macrophages increased adipose tissue inflammation by upregulating inflammatory markers such as TNF-α, IL-6, and IL-1β, as well as genes involved in lipid metabolism." (PMID 37153549, 2023).
Obesity (continued). "Other strategies for treating obesity and DM involve using drugs that act on target molecules, such as dipeptidyl peptidase IV, tyrosine phosphatase 1B, AMP-activated protein kinase, interleukin 6, chemokine ligand 2, and pancreatic lipase." (PMID 37058011, 2023). "Obesity promotes PDAC through secretion of pro-tumorigenic cytokines by adipose tissue resident cells including adipocytes, one which is interleukin-6 (IL-6)." (PMID 36074246, 2023). "Individuals with obesity display a two to three-fold increase in circulating levels of C-reactive protein (CRP), tumor necrosis factor-alpha (TNF-alpha), and interleukin-6 (IL-6), when compared to their normal weight counterparts." (PMID 37139450, 2023). "Pregnant women with obesity and diabetes often have an increase in pro-inflammatory cytokines and adipokines, such as TNF-α, IL-6, IL-1β, leptin, and resistin, which are involved in the inflammatory response." (PMID 37515062, 2023). "The Janus protein tyrosine kinase (JAK)/STAT pathway, is a vital downstream mediator for diverse cytokines (IL-6), hormones (leptin) and growth factors (EGF), and is dysregulated in the context of obesity and metabolic disease, including HCC." (PMID 37361533, 2023). "The serum concentrations of IL-6 and CPR were assessed to determine the effect of fermented garlic and orlistat on the animal model with high-fat diet-induced obesity." (PMID 37959027, 2023). "Paralleling this remodeling of adipose tissue, we found that leptin, resistin, glucagon-like peptide-1 (GLP-1), glucagon, TNF-α, and IL-6 were elevated in serum from DIO-HFD mice relative to CON-LFD, and DIO-VSG suppressed this obesity-driven increase." (PMID 37698918, 2023). "Inflammation has been regarded as a critical mechanism of cognitive dysfunction in human and animal models of obesity, evidenced by the accumulation of proinflammatory cytokines (TNF-α, IL-1β, and IL-6)." (PMID 36334250, 2023). "The link of circulating IL-6, CRP and leptin with obesity and metabolic abnormalities is well documented, with studies showing their positive association with different anthropometric parameters." (PMID 37529617, 2023). "High levels of inflammatory markers such as TNF-alfa, IL -1beta, IL-6, and CRP are elevated in both obesity and PTSD, indicating a common pathological link." (PMID 37374323, 2023). "Further, a VLCKD improves inflammation, reducing TNF-alpha, PAI-1, IL-6, IL-8 and MCP-1, which are strongly involved in the pathophysiology of cardiovascular diseases and obesity." (PMID 37960300, 2023). "It is being used to observe how this particular EVOO component reverses inflammatory parameters (elevated TNF-, IL-1, and IL-6) and inhibits the activation of TLR-4 and NK-kB pathways, which are related to intestinal permeability in obesity." (PMID 36837428, 2023). "Progranulin levels are known to increase in obesity and have been demonstrated to mediate TNF induced increases in the proinflammatory cytokine IL-6 and insulin resistance." (PMID 38057339, 2023). "In obesity, various adipocyte-derived pro-inflammatory cytokines, including TNF-α, interleukin-1β, interleukin-6, monocyte chemotactic protein-1, leptin, and resistin are overproduced, contributing to IR." (PMID 37503477, 2023). "Patients with obesity and type 2 diabetes showed significant reductions in TNF-α, IL-6, CRP, conjugated dienes, and MDA in addition to significant rises in GPx, SOD, and GSH after three months of a lifestyle intervention (diet and physical activity)." (PMID 37109709, 2023). "Overweight and obesity can lead to “low-grade chronic inflammation”, which increases the concentrations of C-reactive protein (CRP) and interleukin (IL)-6 in plasma." (PMID 36353279, 2022). "In both genders, CNTF levels correlated significantly and positively with obesity (BMI, WHR, leptin), diabetes (fasting insulin, HOMA index and HbA1c) and inflammation (IL-6 and hsCRP) indices." (PMID 35585213, 2022).